PLAGL2 (PLAG1 like zinc finger 2)
Description:
Shows weak transcriptional activatory activity.
Synonyms: ZNF900
Tractability: PROTAC: ubiquitination databases record sites on it.
Gene: Protein-coding gene on chromosome 20 (32,192,504 to 32,207,743, reverse strand). Ensembl gene ENSG00000126003.
Subcellular location: Nucleus
Subcellular location (Human Protein Atlas): Nucleoplasm; Cytosol
Gene Ontology:
Molecular function: DNA-binding transcription activator activity, RNA polymerase II-specific; protein binding; sequence-specific DNA binding; DNA-binding transcription factor activity; DNA-binding transcription factor activity, RNA polymerase II-specific
Biological process: regulation of transcription by RNA polymerase II; positive regulation of transcription by RNA polymerase II
Cellular component: nucleus
Genetic constraint (gnomAD): Loss-of-function variants: 7 observed, 28.02 expected, observed/expected ratio (o/e) 0.25, 90% interval 0.14 to 0.47. The upper end of that interval is the gene's LOEUF score, 0.47, which puts it in group 2 of 6, group 1 being the genes least tolerant of losing a copy. Missense variants: 454 observed, 637.65 expected, observed/expected ratio (o/e) 0.71, 90% interval 0.66 to 0.77. Synonymous variants: 234 observed, 259.88 expected, observed/expected ratio (o/e) 0.9, 90% interval 0.81 to 1.
Homologues: Orthologues: chimpanzee PLAGL2 (99% identical), macaque PLAGL2 (99% identical), dog PLAGL2 (99% identical), pig PLAGL2 (99% identical), rabbit PLAGL2 (99% identical), mouse Plagl2 (99% identical), guinea pig PLAGL2 (98% identical), rat Plagl2 (98% identical), zebrafish plagl2 (62% identical), zebrafish plagx (35% identical), Drosophila melanogaster hb (12% identical), Drosophila melanogaster CG12391 (11% identical), and 2 more. Paralogues in human: PLAG1 (51% identical), PLAGL1 (42% identical), PEG3 (16% identical), ZNF518A (14% identical), REST (13% identical), ZNF518B (12% identical), ZBTB35 (11% identical), ZNF274 (11% identical), ZSCAN29 (11% identical), ZNF202 (10% identical), OVOL2 (10% identical), ZNF18 (10% identical), and 17 more.
Diseases named in the same sentence as PLAGL2 in open-access papers:
PLAGL2 is named in the same sentence as 56 diseases in open-access papers, as found by Europe PMC text mining. Sharing a sentence is not in itself a finding about the gene and the disease. The quoted sentences say what the papers report.
colorectal cancer (23 papers, 2017 to 2025). A primary or metastatic malignant neoplasm that affects the colon or rectum. "We previously clarified that PLAGL2 is implicated in the pathogenesis of Hirschsprung disease and colorectal cancer 4,5." (PMID 33391500, 2021). "However, the exact function of PLAGL2 and its underlying mechanism in colorectal cancer (CRC) remain largely unknown." (PMID 31827238, 2020). "In colorectal cancer, the overexpression of PLAGL2 induces the epithelial-to-mesenchymal transition, a key process in metastatic tumor progression, by activating the Wnt/β-catenin signaling pathway." (PMID 38157850, 2024). "In colorectal cancer, several studies have reported that PLAGL2 participates in colorectal cancer progression through activating the Wnt/β-catenin signaling pathway, which accelerates tumor growth and metastasis." (PMID 35565203, 2022). "PLAGL2 also enhances Wnt6 expression at the transcriptional level and promotes the progression of colorectal cancer." (PMID 33391500, 2021). "Emerging evidence has revealed that PLAGL2 acts as an oncogene in various cancers, such as neuroblastoma, non‐small cell lung cancer, prostate cancer, colorectal cancer, and leukemia." (PMID 34586726, 2021). "High PLAGL2 mRNA levels were correlated with a worse prognosis in several cancers, including colorectal cancer, HCC, gastric cancer, breast cancer, and urothelial bladder carcinoma." (PMID 35222518, 2021). "A role of PLAGL2, which needed to be further determined in colorectal cancer, was also identified as a suspected candidate of lung adenocarcinoma as patients with low PLAGL2 expression had a better prognosis at the early stage of disease." (PMID 35222518, 2021). "Collectively, our findings suggest that PLAGL2 mediates EMT to promote colorectal cancer metastasis via β-catenin-dependent regulation of ZEB1." (PMID 31827238, 2020). "MiR-214-3p suppressed the malignant behaviors of colorectal cancer by regulating the PLAGL2/MYH9 axis." (PMID 32413870, 2020). "Pleomorphic adenoma gene like-2 (PLAGL2), a zinc finger protein transcription factor displaying oncogenic function in colorectal cancer (CRC) has been proposed as a target of miR-486-5p." (PMID 32854257, 2020). "Here, our research demonstrated that miR-214-3p inhibits the growth and metastasis of colorectal cancer by targeting PLAGL2." (PMID 32413870, 2020). "In colorectal cancer, the expression of PLAGL2 is obviously increased and acts as a tumor promoting factor." (PMID 32413870, 2020). "It was previously shown that WNT6 expression is positively regulated by CAV1 (a scaffolding protein), UCA1 (a long noncoding RNA), and PLAGL2 (a zinc finger protein) in gastric, bladder, and colorectal cancer, respectively." (PMID 31923345, 2020). "Taken together, our data demonstrated that miR-486-5p promotes colorectal cancer proliferation and migration through activation of PLAGL2/IGF2/β-catenin signal pathway, which is a promising therapeutic target of CRC treatment." (PMID 30305607, 2018). "PLAGL2 was also reported to activate the IGF2 signaling pathway in colorectal cancer." (PMID 36437415, 2023). "PLAGL2 also facilitates the colorectal cancer metastasis through relying on ZEB1." (PMID 35565203, 2022). "Additionally, previous studies indicated that PLAGL2 was involved in the progression of various cancers, including colorectal cancer, lung adenocarcinoma, breast cancer, gastric cancer, and gastrointestinal cancer." (PMID 35222518, 2021). "In addition, PLAGL2 is positively correlated with the degree of tumor invasion in gastrointestinal cancer and colorectal cancer." (PMID 34586726, 2021). "Previously, PLAGL2 was validated to promote EMT process in colorectal cancer via regulating ZEB1." (PMID 34176471, 2021). "PLAGL2 has been confirmed as an oncogene in colorectal cancer and bladder urothelial carcinoma." (PMID 31911754, 2020).
colorectal cancer (continued). "Also interestingly, the 3’UTR of PLAGL2 was found to be independently overexpressed in colorectal cancer cells, and has an independent function in regulating C-Myc and CD44 expression and in promoting cell proliferation and tumor growth." (PMID 32087738, 2020). "And DJ-1 could promote colorectal cancer metastasis by activating PLAGL2-Wnt-BMP4 axis." (PMID 36408174, 2022). "PLAGL2 is co-regulated with POFUT1 by a bidirectional promoter, and the two genes synergistically promote tumorigenesis in colorectal cancer by maintaining stemness and cell-cycle deregulation." (PMID 38157850, 2024). "PLAGL2 has been found to be amplified in a small subset of cancers, and has been reported to promote tumorigenesis together with POFUT1 in colorectal cancer." (PMID 36437415, 2023). "Pleiomorphic adenoma gene-like 2 (PLAGL2) has been proved to activate Wnt/β-catenin signaling pathway and aggravated colorectal cancer development." (PMID 34176471, 2021). "It has been shown that PLAGL2 promoted EMT by USP37-mediated deubiquitination of Snail1 in gastric cancer, as well as β-catenin-dependent regulation of ZEB1 in colorectal cancer." (PMID 34944712, 2021). "Besides, PLAGL2 might promote epithelial-mesenchymal transition and increase metastasis via β-catenin-dependent regulation of ZEB1 in colorectal cancer." (PMID 36879254, 2023).
glioma (13 papers, 2014 to 2023). A benign or malignant brain and spinal cord tumor that arises from glial cells (astrocytes, oligodendrocytes, ependymal cells). "Association of PLAGL2 expression in human glioma tissues with different clinicopathological features." (PMID 35222518, 2021). "Nonetheless, the exact role of PLAGL2 and the underlying mechanism in gliomas continue to remain largely unknown." (PMID 35222518, 2021). "Thus, further investigation was implicated in elucidating whether PLAGL2 overexpression could have a vital role in the progression of glioma." (PMID 35222518, 2021). "Thus, it suggested that PLAGL2 expression could be associated with the progression and development of glioma." (PMID 35222518, 2021). "In the CNS, gains and amplifications of these genes have also been reported in gliomas, and it has been evidenced that PLAGL2 promotes renewal of neural stem cells/progenitor cells by inhibiting their differentiation and thus promoting gliomagenesis." (PMID 37349135, 2023). "Amplification and subsequent overexpression of PLAGL2 was also shown to suppress differentiation in neural stem cells and glioma-initiating cells, in part through aberrant Wnt/β-Catenin signaling in malignant glioma." (PMID 36437415, 2023). "PLAGL2 expression levels were significantly lower in grade III (a-b) compared to grade IV gliomas (c-d)." (PMID 35222518, 2021). "Immunohistochemistry analysis confirmed the overexpression of PLAGL2 protein, which is mainly expressed in the nucleus of glioma." (PMID 35222518, 2021). "Yet, the precise mechanism of PLAGL2 action on gliomas angiogenesis needed to be further investigated." (PMID 35222518, 2021). "Accordingly, GSEA results further indicated that glioma with various PLAGL2 mRNA expression levels had the distinct status of angiogenesis." (PMID 35222518, 2021). "Furthermore, the present study also furthered the understanding of the differential mechanisms positively associated with PLAGL2 expression in the progression of gliomas, which may serve as a favorable prognostic marker in the diagnosis and prognostic of gliomas." (PMID 35222518, 2021). "A high expression of PLAGL2 was observed in the glioma sample and located in the nuclei of tumor cells based on a cohort of HGG samples examined by IHC." (PMID 35222518, 2021). "The contrary PLAGL2 function attributed to different modulatory mechanisms and contributing to glioma tumorigenesis needs further investigation." (PMID 35222518, 2021). "In conclusion, this was the first study that evaluated the upregulated expression of PLAGL2 in gliomas compared with normal brain tissue." (PMID 35222518, 2021). "According to Timer analysis, PLAGL2 was upregulated in bladder, breast, cervix, bile ducts, colorectal, esophagus, kidney, liver, lung, stomach, and CNS cancer compared with normal cases, whereas it was downregulated in renal and thyroid cancers." (PMID 35222518, 2021). "For example, PLAGL2 (Pleomorphic adenomas gene-like 2) and Dishevelled-2 (DVL2) have been shown to activate Wnt pathway in glioblastomas and to sustain self-renewal in glioma CSCs independently of beta-catenin mutations." (PMID 28472177, 2017). "It is noteworthy that the GB-749 glioblastoma hybrid tumor showed retention of glioma-related genes (PLAGL2, GFAP), whereas the lymphoma-derived hybrid tumor retained several B-cell antigen receptor (BCR)-related genes (CD19, CD20, CD71, CD79b)." (PMID 25259521, 2014). "However, few studies reported on the expression of PLAGL2 and its role in the progression and tumor initiation of malignancy in gliomas." (PMID 35222518, 2021). "We found that upregulated PLAGL2 in human glioma compared with normal brain tissues." (PMID 35222518, 2021). "Meanwhile, the results in LGG indicated that patients with glioma also had higher expression levels of PLAGL2 compared with non-tumor tissue, which indicated that PLAGL2 expression was closely linked to the malignancy of glioma." (PMID 35222518, 2021).
glioma (continued). "Herein, we attempted to clarify whether there was any aberrant expression of PLAGL2 in glioma and identify the role of PLAGL2 in glioma progression and prognosis." (PMID 35222518, 2021). "It has been reported that PLAGL2 could impede the differentiation of neural stem cells and glioma-initiating cells by activating Wnt signaling and thus contribute to tumor progression." (PMID 30158634, 2018). "Moreover, we found that Plagl2 reduces neuronal differentiation in the embryonic telencephalon, similar to how it functions in glioma cells." (PMID 30361413, 2018). "Also, highly-expressed PLAGL2 could impede differentiation and expedite self-renewal capacity by modulating Wnt/β-catenin signaling pathway in neural stem cells and gliomas." (PMID 36879254, 2023). "Thus, although the expression and various fundamental carcinogenic processes of PLAGL2 have been extensively involved, the biological role of PLAGL2 in the development and progression of glioma remains largely unknown." (PMID 35222518, 2021). "However, the mechanism and biological functions of PLAGL2 in patients with high-grade glioma (HGG) remain unclear." (PMID 35222518, 2021). "Our study also demonstrated that PLAGL2 was an independent prognostic indicator for PFS and OS in glioma clinical specimens." (PMID 35222518, 2021). "Next, HGG patients with primary glioma and recurrent glioma in CGGA were grouped into cohorts based on the median expression levels of PLAGL2 expression." (PMID 35222518, 2021). "Pleiomorphic adenoma gene like-2 (PLAGL-2), overexpressed in glioblastomas, was found to activate the WNT/β-catenin pathway in neural stem cells and contributes to glioma stem cell self-renewal." (PMID 29081735, 2017). "Our results initially confirmed the PLAGL2 mRNA levels between glioma and non-neoplastic brain tissues in GBM and LGG." (PMID 35222518, 2021). "Based on the ONCOMINE database, PLAGL2 has significantly high expression in glioma tissues (astrocytoma and glioblastoma) as compared with normal tissues." (PMID 35222518, 2021). "In addition, similar enrichment was found related to the gene signatures of migration when the PLAGL2-positive glioma HGG tissues were compared with PLAGL2-negative groups." (PMID 35222518, 2021). "However, while these genes have been described to be expressed in glioma, we found the transcriptional levels of WNT6 are not significantly correlated with CAV1 (r = −0.03, P = 0.66) or PLAGL2 (r = 0.07, P = 0.36) in human GBM, and UCA1 and WNT6 are inversely correlated (r = −0.29, P < 0.001)." (PMID 31923345, 2020).
hepatocellular carcinoma (11 papers, 2010 to 2025). A malignant tumor that arises from hepatocytes. "As an upstream signaling molecule in hepatocellular carcinoma, PLAGL2 can regulate the expression of HIF-1α." (PMID 39102510, 2024). "As an important transcriptional factor, PLAGL2 regulates various cancer processes through different signaling pathways, including hepatocellular carcinoma, gastric cancer, bladder cancer." (PMID 39102510, 2024). "PLAGL2 was recently reported to promote hepatocellular carcinoma progression, metastasis and erlotinib tolerance via the EGFR signaling pathway." (PMID 36600208, 2023). "For hepatocellular carcinoma, PLAGL2 weakens the effect of erlotinib, an anti-EGFR drug, through the EGFR-HIF-1/2α signaling pathway." (PMID 35565203, 2022). "This interaction enhances the transcriptional activity of HIF-1α by stabilizing the PLAGL2 protein, thereby forming a MAPKAPK5-AS1/PLAGL2/HIF-1α signaling loop that promotes the malignant phenotype of hepatocellular carcinoma cells, including proliferation, EMT, and metastasis." (PMID 40861273, 2025). "Silencing PLAGL2 leads to a downregulation of HIF-1α expression in hepatocellular carcinoma." (PMID 39102510, 2024). "Moreover, PLAGL2 overexpression plays a vital role in hepatocellular carcinoma and induces tumor metastasis via EGFR-HIF-1/2α signaling, and cell lines with high PLAGL2 expression have erlotinib resistance, which can be a biomarker for erlotinib therapy." (PMID 35565203, 2022). "Enhanced expression of PLAGL2 was shown to promote lung cancer, colorectal cancer, hepatocellular carcinoma (HCC), and many other cancer types." (PMID 35563824, 2022).
acute myeloid leukemia (9 papers, 2015 to 2024). Acute myeloid leukemia (AML) is a group of neoplasms arising from precursor cells committed to the myeloid cell-line differentiation. "Abdollahi16 found that the overexpression of PLAGL2 not only caused acute granulocytic leukemia in mice, but was also found in 20% of acute myeloid leukemia patients." (PMID 29662235, 2018). "In fact, PLAGL2 was primarily discovered to work as a transcription factor in the pathogenesis of acute myeloid leukemia." (PMID 36600208, 2023). "Aberrant PLAGL2 expression, found in leukemogenesis, participates in the development of acute myeloid leukemia." (PMID 35222518, 2021). "PLAGL2 is involved in a variety of cancers including colon cancer, acute myeloid leukemia, malignant glioma, and lung adenocarcinoma, and PLAGL2 can function as a tumor suppressor by initiating cell cycle arrest and apoptosis." (PMID 31073530, 2019). "Abnormal misexpression of both PLAG1 and PLAGl2 appeared in acute myeloid leukemia-induced amphotropic murine leukemia virus (MLV) strain 4070A48." (PMID 31784561, 2019). "PLAGL2 was shown to upregulate IGF2 expression levels in hematopoietic progenitors of acute myeloid leukemia and IGF2 harbors eight PLAG1/PLAGL2 consensus binding sites." (PMID 36437415, 2023).
gastric cancer (9 papers, 2018 to 2025). A primary or metastatic malignant neoplasm involving the stomach. "In gastric cancer, overexpression of PLAGL2 facilitates the proliferation and migration of gastric cancer cells and contributes to the process of epithelial–mesenchymal transition (EMT) via the USP37-Snail1 axis." (PMID 35565203, 2022). "Many studies have shown overexpression of PLAGL2 in various tumor tissues such as lung cancer, gastric cancer, colorectal adenocarcinoma, and prostate cancer." (PMID 29662235, 2018). "Moreover, PLAGL2 had a critical biological role in promoting the malignant phenotypes of gastric cancer cells through USP37-mediated deubiquitination of Snail protein." (PMID 36879254, 2023). "However, the biological roles of PLAGL2 and its underlying mechanism in gastric cancer (GC) remain unclear." (PMID 33391500, 2021). "In gastric cancer, USP37 enhances cell proliferation and migration by deubiquitinating and stabilizing Snail1 in a PLAGL2-dependent manner." (PMID 40926837, 2025). "PLAGL2 can activate USP37, which in turn acts on Snail 1 to prevent its ubiquitination and promote gastric cancer cell proliferation and metastasis." (PMID 39102510, 2024).
lung adenocarcinoma (8 papers, 2016 to 2023). A carcinoma that arises from the lung and is characterized by the presence of malignant glandular epithelial cells. "Moreover, accumulating reports indicate that PLAGL2 is implicated in the progression of various cancers, including malignant glioma, lung adenocarcinoma, breast, gastric and colorectal cancer." (PMID 27537362, 2016). "Another research indicated PLAGL2 contributed to the development of lung adenocarcinoma in mice model." (PMID 36879254, 2023). "Overexpression of PLAGL2 has been reported to play a role in lung adenocarcinoma development, and may represent a poor prognostic marker in prostate cancer." (PMID 36437415, 2023). "Recent reports further demonstrated that the elevated PLAGL2 expression was associated with the depth of colorectal tumor invasion, and female patients with lung adenocarcinoma who had low PLAGL2 expression and was at an early stage of disease had better prognosis." (PMID 27537362, 2016).
glioblastoma (7 papers, 2013 to 2021). The most malignant astrocytic tumor (WHO grade IV). "Pleomorphic adenoma gene like-2 (PLAGL2) has been implicated in the development and progression of diverse malignancies, including glioblastoma." (PMID 35222518, 2021). "In glioblastoma, PLAGL2 suppresses neural stem cell differentiation by regulating Wnt/β-catenin signaling." (PMID 34249670, 2021). "Regional gains encompassing PLAGL2 gene were also confirmed in glioblastoma, AML samples and the immortalized lung epithelial cell lines." (PMID 27537362, 2016). "Aberrant PLAG2 expression was found in the development of the expression of PLAGL2 bladder urothelial carcinoma, AML, gastrointestinal cancers, and glioblastoma." (PMID 35222518, 2021).